MIR1304 (microRNA 1304)
Synonyms: hsa-mir-1304; MIRN1304
Gene: MicroRNA gene on chromosome 11 (93,733,674 to 93,733,764, reverse strand). Ensembl gene ENSG00000284458.
Diseases named in the same sentence as MIR1304 in open-access papers:
MIR1304 is named in the same sentence as 2 diseases in open-access papers, as found by Europe PMC text mining. Sharing a sentence is not in itself a finding about the gene and the disease. The quoted sentences say what the papers report.
breast carcinoma (1 paper, 2025). "For instance, the G allele for MIR1304 is a risk allele for AA breast cancer and affects circulating MIR1304 levels in the serum exosomes, activating cancer‐associated adipocytes." (PMID 40998459, 2025).
MIR1304 also shares sentences with these, for which no sentence is quoted: cancer (1 paper).